SSBP3-AS1 (SSBP3 antisense RNA 1)
Synonyms: C1orf191; MSTP128; MST128
Gene: Long non-coding RNA gene on chromosome 1 (54,236,440 to 54,239,063, forward strand). Ensembl gene ENSG00000198711.
Subcellular location: Secreted